IL25 (interleukin 25)
Diseases named in the same sentence as IL25 in open-access papers (continued):
Sharing a sentence is not in itself a finding about the gene and the disease.
asthma (continued). "In contrast, increased expression of IL-33 and TSLP, but not IL-25, was reported in asthma patients in London, Poland, and New York, New York." (PMID 33945508, 2021). "Together, these studies suggest that the CD39–extracellular ATP axis may regulate IL-25, IL-33, and TSLP in asthma." (PMID 33945508, 2021). "We hypothesized that the differentially expressed epithelial miRNAs between the 2 asthma subsets may contribute to IL-25, IL-33, and TSLP expression in asthma." (PMID 33945508, 2021). "Consequently, more extracellular ATP was accumulated, leading to higher expression of IL-25 and TSLP and more prominent type 2 inflammation in type 2–high asthma." (PMID 33945508, 2021). "Administration of anti-IL-25 and anti-TSLP antibodies during ovalbumin-induced asthma could reduce the infiltration of inflammatory cells into airways, as well as local expression of IL-4, IL-5 and IL-13." (PMID 34084159, 2021). "ILC2s do not depend on T cells and secrete a large number of type 2 cytokines (such as IL-4, IL5, IL-9, and IL-13) under the function of IL-25, IL-33 and thymic stromal lymphopoietin (TSLP) to participate in asthma, virus infection and worm-host defense related with the type 2 immune response." (PMID 33514798, 2021). "In a mouse model of asthma, IL-25-induced ILC2s and IL-33-induced ILC2s contributed 50~80% of the total IL5 and IL-13 production in the lung, although stimulation with IL-25 or IL-33 separately did not cause excessive lung reactions." (PMID 34177881, 2021). "However, CD127low ILC2s have also been identified in asthma patients and mice, and it is worth noting that CD127 expression was shown to be decreased after IL-25 stimulation." (PMID 34177881, 2021). "This indicates that the more prominent accumulation of airway ATP may be responsible for the elevated IL-25 and TSLP expression in type 2–high asthma." (PMID 33945508, 2021). "Although Tezepermab, a biologic that targets TSLP for treatment, was reported to reduce the frequency of asthma exacerbations, the role of ILCS2, including IL25 and IL-33, is not fully understood, and we need to elucidate the full mechanism of its production and develop new treatment options." (PMID 32823491, 2020). "An antibody that neutralizes the human receptor for IL-17 (brodalumab, which can neutralize the activities of IL-17A, IL-17F and IL-25) has little effect on patients with mild to moderate asthma in clinical trials and has not achieved satisfactory results." (PMID 32620122, 2020). "IL-25 and TSLP are epithelial-derived cytokines that play an essential role in stimulating Th2 cytokine response and initiating airway type 2 inflammation in asthma." (PMID 31885750, 2019). "Furthermore, profibrotic cytokines and fibrogenic mediators, such as IL-11, IL-17, IL-17E (also known as IL-25), TGF-α, TGFβ1, and matrix metalloproteinase-9, are involved in airway remodeling in asthma and polyp formation in CRS with nasal polyps (CRSwNP)." (PMID 30764556, 2019). "For the epithelial environment stage of asthma (allergic sensitization stage), air exposure to allergens induces the secretion of proinflammatory cytokines (Group 1) in the airway epithelium, such as TSLP, IL-6, IL-8, TNF-α, IL-25, IL-33, and GM-CSF." (PMID 31284537, 2019). "We investigate whether the augmented Th2-cytokines in CRS might be related to sinonasal tract ILC2s corresponding to enhanced IL-25, IL-33 and TSLP release in severe asthmatics, and be involved in asthma control." (PMID 28199345, 2017). "In contrast, the expression of TSLP, IL-25, and IL-33 in non-severe asthma patients with CRS group was very weak (respectively)." (PMID 28199345, 2017). "We suggest that this novel model of viral-induced asthma exacerbation has translational value and is suited for in vivo studies involving pharmacological effects on exacerbation-induced expression of IL-33, TSLP and IL-25, as well as PRRs." (PMID 26879906, 2016).
asthma (continued). "That is, keratinocyte-derived IL-25, IL-33 and/or TSLP may be involved in sensitization to allergens, contributing to the development of not only atopic dermatitis but also asthma." (PMID 26230091, 2015). "Interestingly, in a mouse model of virus-induced asthma exacerbation, administration of Poly I:C induced IL-33 gene expression, but not IL-25, in wild-type mice." (PMID 41576028, 2026). "Moreover, sputum IL-25 concentrations are higher in atopic than non-atopic asthma and correlate with disease severity." (PMID 41303221, 2025). "Furthermore, airway damage increases epithelial permeability, enhancing allergen exposure and promoting the release of alarmins [Interleukin-25 (IL-25), Interleukin-33 (IL-33), and thymic stromal lymphopoietin (TSLP)] by epithelial cells, which in turn induce Th2-high asthma." (PMID 40678720, 2025). "Furthermore, since HMPV and RSV infection in children has been reported to drive type 2 immune responses, we analyzed the response of epithelial alarmins IL-25, IL-33, and TSLP, which play significant roles in the pathophysiology of asthma by promoting inflammation and airway hyperresponsiveness." (PMID 40143308, 2025). "Single blockade of TSLP, IL-25, or IL-33, which stimulate ILC2 and Th2 cells to release type 2 cytokines, decreases airway inflammation and hyperresponsiveness in murine asthma models, and concurrent blockade of all three cytokines produces more pronounced effects." (PMID 39962262, 2025). "Additionally, co-stimulation with PM2.5 and the house dust mite allergen Der p1 increased the production of malondialdehyde (MDA) and mRNA and protein expression of IL25, IL33, and CCL17, which are hallmarks of innate immunity and asthma, in a human bronchial epithelial cell line." (PMID 39456509, 2024). "Furthermore, in a mouse model of asthma, ST2 knockout reduced airway inflammation, Th2 cytokine expression and fibrosis-related protein deposition, all of which were further reduced by additional blockade with anti-TSLP and anti-IL-25 antibodies." (PMID 38609094, 2024). "LTRAs alone might increase inflammation and exacerbate asthma by inducing the production of IL-25, IL-33, and TSLP; therefore, LTRA monotherapy may not be an appropriate therapeutic option for asthma." (PMID 36674744, 2023). "In a previous study, plasma IL-25 concentrations, IL25 mRNA levels in bronchial brushings, and the expression of the IL-25 receptors IL-17RA and IL-17RB on eosinophils in subjects with severe asthma were observed to be significantly higher than those in normal subjects." (PMID 36674744, 2023). "ILC2 rapidly proliferate in response to IL-25 and production of IL-25 by epithelial cells induces chemokines including TARC, eotaxin, and macrophage-derived chemokine (MDC), thereby playing a role in in airway remodeling and angiogenesis, which contributes to asthma severity." (PMID 35406669, 2022). "Interestingly, HDM challenge also markedly and significantly elevated the expression of IL-25, IL-33 and TSLP (three cytokines also thought to a play pivotal role in the initiation of asthma) in the lung tissue of both WT and Il9−/−mice compared with saline challenge." (PMID 35524325, 2022). "Indeed, IL-25 has been reported to induce VEGF expression and promote angiogenesis by human vascular endothelial cells in vitro, and in vivo in a mouse model of asthma where intranasal administration of IL-25 increased VEGF expression and airway vascularity." (PMID 36263033, 2022). "The production and release of epithelial cytokines, including IL-33, IL-25, and TSLP, lead to the recruitment and activation of ILC2, which secretes mediators, such as IL-5 and IL-13, that augment allergic inflammation in the pathogenesis of virus-induced asthma exacerbation." (PMID 35008429, 2021).
asthma (continued). "In addition to Th17 cells and Treg cells, many immunoregulatory cells, such as Th2 cells, Th1 cells, innate lymphoid cells, dendritic cells, natural killer T cells, and TH9 cells, and many endogenous cytokines related to asthma, such as IL4, IL-5, IL13, IL22, and IL25, are also involved." (PMID 32620122, 2020). "The specific cellular source of cytokine production in asthma is unclear, although evidence shows that allergens, including HDM, may activate airway epithelium leading to the release of mediators including IL-25, IL-33, and thymic stromal lymphopoietin, which activate ILC2." (PMID 30122959, 2018). "Moreover, we found a much higher secretion of IL-5, IL-13 and IL-25 in the asthma group (P< 0.05), while no significant changes in the anti-IL-25 group were observed (P> 0.05)." (PMID 27617447, 2016). "Recent studies have found that cytokine alarmins, including thymic stromal lymphopoietin (TSLP), IL-25, and IL-33, produced by epithelial cells and some hematopoietic cells play important roles in the promotion of TH2 cell development and the initiation of asthma pathogenesis." (PMID 27378934, 2016). "We hypothesize that iNKT2 cells may also be increased in IL-25-high asthmatic patients facilitating the generation of “Th2-high” asthma, as opposed to a severe, neutrophil-mediated, steroid-insensitive disease." (PMID 26482437, 2015). "Thus, airway epithelial cells are also active players in the pathogenesis of asthma through epithelial cytokines including IL-33, TSLP, and IL-25, which are produced and released by epithelial cells in response to various exogenous stimuli or by cellular damage." (PMID 23496815, 2013). "Moreover, elevated levels of IL-33, IL-25 and/or TSLP were observed in the inflamed skin of patients with atopic dermatitis, in lung smooth muscle cells and epithelial cells from patients with asthma, and/or in sera from patients with AR." (PMID 24205109, 2013). "This activation in turn increased the production of IL-33, IL-25, and thymic stromal lymphopoietin (TSLP); raising the possibility that resident ILCs2 might be activated by these stroma-derived cytokines in HDM-induced asthma." (PMID 23209480, 2012). "This suggests that lack of endogenous IL-25 may contribute to pathogenesis of severe asthma." (PMID 37898756, 2023). "Interestingly, the expression of BIRC3 in GSE76262 was significantly positively correlated with inflammatory cytokines IL-4, IL-5, IL-13, and IL-25 expression (p < 0.05), which implied that BIRC3 may play an important role in the pathogenesis of inflammation in asthma." (PMID 35287655, 2022). "However, IL-4 and IL-25 were similar in asthma patients with or without comorbid AR." (PMID 35348596, 2022). "Thus, it has been questioned whether blocking IL-25 against its receptor IL-17BR could inhibit the expression of IL-13 and IL-5 via nuocytes, and further protect against inflammation in ovalbumin (OVA) induced mouse-model of asthma." (PMID 27617447, 2016). "These cells have no impact on T-cells mediated allergen-induced asthma and therefore are not necessary for allergen-specific Th2 differentiation and IL-17RB+ lung-resident cells, probably nuocytes, that trigger Th2 responses in a manner dependent on IL-33 and/or IL-25." (PMID 23209480, 2012). "Based on our analysis of the data from a cohort with severe asthma in the U-BIOPRED study, the protein level of IL-25 was significantly decreased in sputum from non-smoker severe asthma (n = 37) compared to controls (n = 18)." (PMID 37898756, 2023). "Probiotic and prebiotic treatments reduced the levels of Th2 cytokines (IL-4, IL-5, IL-13, IL-17, IL-25, and IL-33) and increased IFN-γ level in the BALF of asthmatic mice as compared to the non-treated asthma group." (PMID 35296330, 2022). "In Korea, plasma IL-25, but not IL-33 or TSLP, was increased in patients with aspirin-exacerbated respiratory disease characterized by asthma, nasal polyps, and chronic eosinophilic sinusitis." (PMID 33945508, 2021).
asthma (continued). "Here, in a different cohort of asthmatic patients, using ELISA and qPCR, we found that airway expression of IL-25 and TSLP, but not IL-33, was elevated in type 2–high asthma patients." (PMID 33945508, 2021). "IL-25 and TSLP, although not members of the alarmin family, are cytokines that act together to and share similar features with IL-33 in asthma inflammatory pathways." (PMID 34608100, 2021). "Our data suggest that airway expression of IL-25 and TSLP, but not IL-33, is elevated in type 2–high asthma." (PMID 33945508, 2021). "Blockade of IL-25 or the absence of its receptor, IL-17RB, reduces Th2 cytokine production, mucus production, and/or AHR in murine RSV infection and RSV-induced asthma exacerbation models." (PMID 29915592, 2018). "In severe asthma patients with CRS, there was an upregulated expression of IL-33, IL-25 and TSLP in their nasal tissues, compared to those in non-severe asthma patients." (PMID 28199345, 2017). "The mRNA expression of TSLP, IL-25 and IL-33 was significantly higher in patients with severe asthma and CRS compared to those of non-severe asthma with CRS." (PMID 28199345, 2017).
allergic disease (69 papers, 2010 to 2026). An immune response that occurs following re-exposure to an innocuous antigen, and that requires the presence of existing antibodies against that antigen. "ILIR1 is a mediator of many cytokine-induced immune and inflammatory responses, while IL25 has been shown to be associated with type 2 immune responses responsible for the development of allergic diseases." (PMID 39591149, 2024). "Nuclear alarmins (TSLP, IL-33, IL-25) appear to have a critical role in IgE-mediated allergies but are also implicated in entities such as eosinophilic esophagitis." (PMID 37048784, 2023). "A respiratory allergic reaction caused by cytomegalovirus (CMV) is also associated with IL-25 secretion." (PMID 36119076, 2022). "In certain circumstances, IL-25 involves in the development of allergic diseases caused by the pathogenic infection." (PMID 36119076, 2022). "IECs release cytokines, namely IL-33, IL-25, and TSLP (respectively encoded by Il33, Il25, and Tslp), that work as immune alarm signals in response to cellular stress or injury and are involved in the pathophysiology of allergic disease." (PMID 33803079, 2021). "IL-17E (IL-25) produces a particularly important activity on acquired and innate immune responses not only because it is linked to allergic disease, but also because it plays a protective role in helminthic parasite infection." (PMID 25152827, 2014). "On the one hand, IL-25 activates type 2 immunity via the relevant cytokines, including IL-4, IL-5, and IL-13, which are associated with the development of pathogenic infection-related allergic diseases." (PMID 36119076, 2022). "Similar to IL-33, TSLP and IL-25 can also be detected in increased amounts in the tissues of patients with asthma or atopic dermatitis, and genome-wide analyses demonstrate an association of these cytokines with allergic diseases." (PMID 33615121, 2021). "Epithelial cytokines, including interleukin-25 (IL-25), are produced in the colon and are critical for protection from parasites, but can also be pathogenic in the context of inflammatory bowel diseases and allergy." (PMID 27165713, 2016). "Hence, we speculate that the role of IL-25 in bronchial asthma patients is also applicable in the ARAs and that eosinophils are associated with allergic diseases, such as AR and bronchial asthma." (PMID 30345318, 2018). "Research on the role of IL-25 in reperfusion injury is limited because studies on IL-25 have concentrated on its connection with allergy, immunomodulation, and tumor immunity." (PMID 38879568, 2024). "IL-25 is involved in enhancing the severity of allergic reactions through the induction of a type 2 immune response." (PMID 37005677, 2023). "IL-25 is an alarmin released by epithelial cells during allergies and helminth infection, which can drive a multi-faceted type-2 response and restore immunity in genetically susceptible mice when administered exogenously." (PMID 37316905, 2023). "The positive effect of IL-25 in numerous allergy and respiratory disorders has currently been established." (PMID 37005677, 2023). "The biological effect of IL-25 and IL-33 in driving type-2 immune response was extensively demonstrated in the allergy and helminth infection model." (PMID 37337050, 2023). "IL-17E, also known as IL-25, is involved in the pathogenesis of fungal infections, allergies, and autoimmune disorders." (PMID 38202170, 2023). "In patients with allergic diseases such as allergic asthma, local cells in the affected tissue, including eosinophils, basophils, mast cells, and keratinocytes, express both IL-25 and IL-25R, and further drive an allergic response." (PMID 35406669, 2022). "PERK mediates the IL-25-induced airway epithelial cell apoptosis to contribute to allergy development." (PMID 35910793, 2022). "Pro-inflammatory cytokines (e.g., IL-12, IL-25 and IL-13) play an important role in driving allergic conditions including allergic asthma; IL-33, IL-4 and IL-5 are key factors that drive allergy." (PMID 34638811, 2021).